PLXNA3 (plexin A3)
Description:
Coreceptor for SEMA3A and SEMA3F. Necessary for signaling by class 3 semaphorins and subsequent remodeling of the cytoskeleton. Plays a role in axon guidance in the developing nervous system. Regulates the migration of sympathetic neurons, but not of neural crest precursors. Required for normal dendrite spine morphology in pyramidal neurons. May play a role in regulating semaphorin-mediated programmed cell death in the developing nervous system. Class 3 semaphorins bind to a complex composed of a neuropilin and a plexin. The plexin modulates the affinity of the complex for specific semaphorins, and its cytoplasmic domain is required for the activation of down-stream signaling events in the cytoplasm.
Synonyms: PLXN4; SEX; XAP-6; 6.3; Plxn3; HSSEXGENE
Tractability: Antibody: its Gene Ontology location is reachable by antibodies, with high confidence; UniProt places it where antibodies can reach, with medium confidence; UniProt predicts a signal peptide or a membrane-spanning region; the Human Protein Atlas places it where antibodies can reach. PROTAC: ubiquitination databases record sites on it; its protein half-life has been measured.
Gene: Protein-coding gene on chromosome X (154,458,280 to 154,477,779, forward strand). Ensembl gene ENSG00000130827.
Subcellular location: Cell membrane
Subcellular location (Human Protein Atlas): Cytosol; Golgi apparatus; Plasma membrane
Pathways (Reactome):
Developmental Biology: CRMPs in Sema3A signaling; SEMA3A-Plexin repulsion signaling by inhibiting Integrin adhesion; Sema3A PAK dependent Axon repulsion
Gene Ontology:
Molecular function: protein binding; semaphorin receptor activity; signaling receptor activity
Biological process: axon guidance; branchiomotor neuron axon guidance; facial nerve structural organization; hippocampus development; motor neuron axon guidance; neuron projection guidance; positive regulation of cytoskeleton organization; pyramidal neuron development; regulation of cell migration; semaphorin-plexin signaling pathway; synapse assembly; trigeminal nerve structural organization; gonadotrophin-releasing hormone neuronal migration to the hypothalamus; negative chemotaxis; neuron projection extension; olfactory nerve formation; regulation of axon extension involved in axon guidance; regulation of axonogenesis; regulation of chemotaxis; telencephalon development
Cellular component: plasma membrane; semaphorin receptor complex
Homologues: Orthologues: chimpanzee PLXNA3 (99% identical), macaque PLXNA3 (97% identical), rabbit PLXNA3 (96% identical), mouse Plxna3 (95% identical), rat Plxna3 (95% identical), pig PLXNA3 (94% identical), dog PLXNA3 (94% identical), guinea pig PLXNA3 (94% identical), tropical clawed frog plxna3 (75% identical), zebrafish plxna3 (74% identical). Paralogues in human: PLXNA1 (67% identical), PLXNA4 (60% identical), PLXNA2 (60% identical), PLXNB1 (35% identical), PLXNB3 (33% identical), PLXND1 (31% identical), PLXNB2 (31% identical), PLXNC1 (21% identical).
Diseases named in the same sentence as PLXNA3 in open-access papers:
PLXNA3 is named in the same sentence as 27 diseases in open-access papers, as found by Europe PMC text mining. Sharing a sentence is not in itself a finding about the gene and the disease. The quoted sentences say what the papers report.
breast carcinoma (3 papers, 2020 to 2025). "PLXNA3, a member of the plexin family originally implicated in axon guidance, has recently been linked to oncogenic processes in breast cancer and nephroblastoma." (PMID 40963600, 2025). "Our analysis showed that PLXNA3, B2, and C1 were significantly upregulated, and NRP1, NRP2, PLXNA1, A2, A4 were significantly downregulated, while the rest of the members (PLXNB1, B3 and D1) were not differentially expressed in breast cancer tumors." (PMID 32640719, 2020).
autism (2 papers, 2021). Persistent deficits in social interaction and communication and interaction as well as a markedly restricted repertoire of activity and interest as well as repetitive patterns of behavior. "A previous study has described an ASD patient from Maghreb carrying a rare inherited missense variant (p.D863E) in PLXNA3, suggesting that it may contribute to autism." (PMID 33860439, 2021).
colorectal cancer (2 papers, 2025 to 2026). A primary or metastatic malignant neoplasm that affects the colon or rectum. "This pattern was particularly consistent in colorectal cancer, reinforcing PLXNA3’s relevance as a tumor-associated gene within the digestive tract." (PMID 40963600, 2025). "To validate our bioinformatics findings at the protein level, we performed IHC staining for PLXNA3 in 22 clinical samples of colorectal cancer." (PMID 40963600, 2025). "This study identifies PLXNA3 as a novel immune-related biomarker in colorectal cancer and elucidates its multifaceted role in tumor progression, immune evasion, and therapeutic resistance." (PMID 40963600, 2025). "Among these, PLXNA3 emerged as a gene of particular interest due to its comparable model-derived importance score, coupled with its limited prior characterization in colorectal cancer immunity." (PMID 40963600, 2025). "Plexin A3 (PLXNA3) is involved primarily in nervous system development, but its function in colorectal cancer (CRC) remains poorly understood." (PMID 42223791, 2026). "Notably, we did not directly assess the predictive value of PLXNA3 in the context of immune checkpoint inhibitor (ICI) therapy, due to the lack of large-scale, colorectal cancer–specific immunotherapy cohorts with available treatment outcome data." (PMID 40963600, 2025).
autoimmune disorders (1 paper, 2023). "We performed an X chromosome cis-eQTL analysis in female naïve and LPS-stimulated monocytes and identified 6 eQTL-genes unique to LPS-stimulated female monocytes, some of which have been previously associated with autoimmune disorders, including PLXNA3." (PMID 38072919, 2023).
gonadal dysgenesis (1 paper, 2022). A congenital disorder characterized by the presence of extremely hypoplastic gonads preventing the development of secondary sex characteristics. "However, our data suggest that association of PLXNA3 LOF variants with CHH is unlikely, since one man (DSD 15), presented with gonadal dysgenesis/TRS and with elevated gonadotropins was found to harbor a hemizygous LOF variant in PLXNA3 (p.V263fs)." (PMID 36110220, 2022).
hypogonadotrophic hypogonadism (1 paper, 2019). "One male carrying PLXNA3 D1710N had hypogonadotrophic hypogonadism." (PMID 30661757, 2019).
infertile (1 paper, 2015). "In our previous study, random distribution and depletion of H3K9ac interaction in many loci (for example, CTSD, FLNA, MCF2L, PLXNA3, SG3GLB2, TH) of infertile men sperm have been confirmed." (PMID 25806092, 2015).
intellectual disability syndrome (1 paper, 2023). "In contrast, genomic sequencing analyses in ASD patients with neurodevelopmental disorders identified 26 novel candidate genes, including Plexin-A3, which has now been found to be associated with intellectual disability syndrome." (PMID 38133141, 2023).
lymph node metastasis (1 paper, 2025). "The IHC results further validated PLXNA3 overexpression at the protein level, and a trend of increasing expression with higher N stages suggested a potential link to lymph node metastasis." (PMID 40963600, 2025).
metastatic tumor (1 paper, 2020). "In addition, PLXNA3, B2, and B3 had further increased, while NRP2 and PLXNA2 had further decreased expression in metastatic tumors than in primary tumors although none of the differences were significant due to the small number of metastatic tumor samples (n = 7)." (PMID 32640719, 2020).
osteoporosis (1 paper, 2022). A condition of reduced bone mass, with decreased cortical thickness and a decrease in the number and size of the trabeculae of cancellous bone (but normal chemical composition), resulting in increased fracture incidence. "This study aimed to explore the associations of genetic variants in the semaphorin 3A (SEMA3A) signaling pathway genes, including SEMA3A, NRP1, PLXNA1, PLXNA2 and PLXNA3 with osteoporosis (OP) risk and bone mineral density (BMD) in a Chinese Han older adult population." (PMID 36425469, 2022).
cancer (6 papers, 2015 to 2025). A tumor composed of atypical neoplastic, often pleomorphic cells that invade other tissues. "In the univariate Cox model, PLXNA3 consistently appeared as a high-risk factor (HR >1) across several cancer types, with particularly strong statistical significance in COAD." (PMID 40963600, 2025). "PLXNA3 was another gene upregulated in the majority of the tested cancers and the increased expression was associated with worse OS and PFI of COAD, KIRC, brain lower grade glioma (LGG), MESO, SARC, UCEC, uveal carcinosarcoma (UVM), and PRAD." (PMID 32640719, 2020). "To explore the prognostic relevance and biological function of PLXNA3, we initiated our investigation with a pan-cancer screening strategy to broadly evaluate its expression patterns and clinical significance across multiple tumor types." (PMID 40963600, 2025). "We first examined transcriptional regulation by identifying the top 25 transcription factors (TFs) most positively and negatively correlated with PLXNA3 expression in each TCGA cancer type." (PMID 40963600, 2025). "Among these, PLXNA3, HLA-E, DDX58, IKBKE, HSPA6, SOS2, and HSPA1A stood out, with significantly elevated expression levels in LIHC compared to other cancer types." (PMID 39000042, 2024). "For the correlation with DNAss score, PLXNA1 and A2 showed positive correlation (r = 0.38 and 0.18, respectively), while all other members showed negligible (|r| < 0.17) or insignificant correlation (PLXNA3 and NRP2) across all cancer types." (PMID 32640719, 2020). "The other major cluster is further separated into several subclusters, with one subcluster including PLXNA1, PLXNA3, and SEMA3F showing predominantly increased expression in cancer tumors." (PMID 32640719, 2020). "Data from other cancers suggest the involvement of PLXNA2 and PLXNA3 in cell extension and invasion." (PMID 26962861, 2016).
tumor (5 papers, 2016 to 2026). "Although sample size precluded statistical testing, a trend of increasing PLXNA3 expression with advancing N stage was observed, suggesting possible association with nodal metastasis and tumor progression." (PMID 40963600, 2025). "Transcription factor (TF) and microRNA (miRNA) correlation analyses revealed potential upstream regulators of PLXNA3 linked to tumor stemness and immune suppression." (PMID 40963600, 2025). "Although PLXNA3 has been implicated in neural development and tumor metastasis in several malignancies, its role in gastrointestinal cancers remains largely uncharacterized." (PMID 40963600, 2025). "PLXNA1 and PLXNA3 were also reported to promote tumor growth and associate with poor prognosis." (PMID 32640719, 2020). "In normal tissues, PLXNA3 expression was primarily enriched in the colorectal region of the gastrointestinal tract, whereas in tumor tissues, its expression was concentrated in gastric and esophageal organs." (PMID 40963600, 2025). "Expression comparisons between tumor and normal tissues from TCGA confirmed significant upregulation of PLXNA3 in gastrointestinal cancers." (PMID 40963600, 2025). "Spatial visualization revealed that PLXNA3 was predominantly expressed in tumor-enriched regions across all primary CRC samples." (PMID 40963600, 2025). "Lastly, to assess how PLXNA3 links with broader tumor phenotypes, we integrated CancerSEA functional state scores and conducted correlation analysis across 14 tumor-related biological processes." (PMID 40963600, 2025). "Quantitative comparison between tumor and adjacent normal tissues revealed significantly higher PLXNA3 IHC scores in tumor samples (p = 0.0005), supporting the translational relevance of our transcriptomic predictions." (PMID 40963600, 2025). "High PLXNA3 expression correlated with advanced tumor stage and metastasis." (PMID 42223791, 2026). "To further elucidate the mechanistic basis by which PLXNA3 may contribute to tumor progression and immune suppression, we performed a multi-layered regulatory and functional analysis across gastrointestinal cancers." (PMID 40963600, 2025). "In all CRC samples, PLXNA3 expression was significantly higher in malignant regions compared to non-malignant areas (p < 0.05), underscoring its spatial enrichment in tumor tissue." (PMID 40963600, 2025). "In tumor cells, PLXNA3 showed consistent negative correlations with pathways that are typically associated with tumor-suppressive functions, including DNA repair, DNA damage response, and quiescence." (PMID 40963600, 2025). "In summary, based on our systematic analyses of NRPs and PLXNs in terms of their expression, association with patient survival, immune subtype, and tumor infiltration, we found that NRP1, NRP2, PLXNA1, PLXNA3, PLXNB3, PLXNC1, PLXND1 were mainly associated with poor prognosis." (PMID 32640719, 2020). "PLXNA3 stood out for its combination of high expression and strong dependency across multiple digestive system cancer cell lines, highlighting its potential functional relevance in tumor maintenance and positioning it as a candidate of interest for downstream investigation." (PMID 40963600, 2025). "Immunohistochemistry (IHC) confirmed PLXNA3 overexpression in tumor tissues and its correlation with nodal metastasis." (PMID 40963600, 2025). "Finally, paired sample analyses within TCGA confirmed significantly higher PLXNA3 expression in tumor tissues compared to adjacent non-tumor controls across COAD, READ, STAD, and ESCA." (PMID 40963600, 2025).
gastrointestinal tumors (1 paper, 2025). "Following the spatial transcriptomic observation of PLXNA3 enrichment in malignant epithelial regions, we performed a single-cell level analysis across gastrointestinal tumors to evaluate its expression in diverse cell types, particularly immune populations." (PMID 40963600, 2025).
PLXNA3 also shares sentences with these, for which no sentence is quoted: anthrax (1 paper); asthenia (1); asthma (1); Atrophy (1); congenital hypogonadotropic hypogonadism (1); digestive system cancer (1); gastric cancer (1); glioma (1); Nephroblastoma (1); neurodevelopmental disorder (1); prostate carcinoma (1); rectal cancer (1); X-linked disease (1).